PKMYT1 (protein kinase, membrane associated tyrosine/threonine 1)
Diseases named in the same sentence as PKMYT1 in open-access papers (continued):
Sharing a sentence is not in itself a finding about the gene and the disease.
tumor (continued). "In tumor cells, by arresting the cycle, PKMYT1 expression is important for cell survival and growth." (PMID 37091166, 2023). "RP-6306 treatment induced pan-γH2AX in an HCC1569 breast cancer cell line, indicating that tumour-derived CCNE1 amplification also renders cells vulnerable to DNA damage induction following PKMYT1 inhibition." (PMID 35444283, 2022). "Together, these data indicate that PKMYT1 inhibition displays single-agent tumour growth inhibition in a variety of CCNE1-amplified models." (PMID 35444283, 2022). "To inhibit PKMYT1, we developed RP-6306, an orally bioavailable and selective inhibitor that shows single-agent activity and durable tumour regressions when combined with gemcitabine in models of CCNE1 amplification." (PMID 35444283, 2022). "A retrospective analysis of large sample data from GSE96058 and METABRIC cohorts showed that PKMYT1 expression was higher in high tumor grade, advanced tumor size stage, advanced lymph node metastasis stage, HER2 positive status, and ER negative status." (PMID 36793346, 2022). "Meanwhile, miR-601 inhibited the expression of PKMYT1 at the post-transcriptional level, thus exerting its tumor suppressive function." (PMID 35461324, 2022). "According to previous literature, PKMYT1 promoted tumor cell proliferation and apoptosis resistance via activating the MAPK signaling pathway in gastric cancer." (PMID 35461324, 2022). "In our study, we demonstrated for the first time that PKMYT1 was a prognostic marker according to public databases and promoted tumor progression with experiments in BC." (PMID 36793346, 2022). "We conclude that PKMYT1 inhibition is selectively cytotoxic to tumour cells displaying CCNE1 amplification, consistent with the genetic observations made in the isogenic cell lines." (PMID 35444283, 2022). "In our studies, we found that miR-601 exerted its anti-tumor function via targeting PKMYT1 at post-transcriptional level." (PMID 35461324, 2022). "Genome-scale CRISPR–Cas9-based synthetic lethality screens identify PKMYT1 as a potential therapeutic target in tumours with CCNE1 amplification." (PMID 35444283, 2022). "This analysis identified PKMYT1 as the gene that displayed the strongest dependency in CCNE1-amplified tumour cell lines." (PMID 35444283, 2022). "Significant reduction of tumor growth visualized by decreased Ki67 staining and PKMYT1 expression, but increased CC3 expression, were detected in PKMYT1AR ASOs groups compared to control group." (PMID 34856993, 2021). "The research revealed that high PKMYT1 expression correlated significantly with higher stage, grade and the stage of tumor, regional lymph nodes, and distant metastasis." (PMID 34959223, 2021). "Consistently, PKMYT1 was identified to be highly expressed in NSCLC cancerous cell lines, and knockdown of PKMYT1 inhibited the cell proliferation, colony formation and migration abilities of tumor cells." (PMID 34856993, 2021). "Both in vitro and in vivo functional assays were performed to investigate the functional role of PKMYT1AR/miR-485-5p/PKMYT1 axis on regulating cell proliferation, migration and tumor growth." (PMID 34856993, 2021). "It is well-established that CDK1 is a key molecule in the progression of mitosis, and thus PKMYT1 is thought to play important roles in the regulation of the cell cycle and tumor biology." (PMID 32180804, 2020). "Several targeted compounds showed an inhibitory activity on WEE1 and PKMYT1 kinases and their efficacy was proven in a number of tumor types." (PMID 32958072, 2020). "Most of these interactions involved cell cycle related genes, like SPC24 and CDC20 (regulated by the anti-oncomiR miR-139), and PKMYT1 (regulated by the tumour suppressor miR-195)." (PMID 28387377, 2017). "PKMYT1, a critical cell cycle regulator at the G2/M checkpoint, has emerging but less defined roles beyond proliferation, with potential intersections in metabolic signaling and tumor microenvironment influence." (PMID 40821907, 2025).
tumor (continued). "PKMYT1 ablation inhibits tumor growth and proliferation in vitro and in vivo." (PMID 38570712, 2024). "PKMYT1 was identified as a pivotal tumor vulnerability in PDAC." (PMID 38570712, 2024). "Therefore, inhibiting PKMYT1 not only leads to suppression of tumor growth by regulating its own expression, but also exhibits an additional unexpected inhibitory effect through PLK1 regulation." (PMID 38570712, 2024). "Considering CCNE1 amplification causes replication stress that activates the DNA replication fork stabilizer and regulator of G2/M checkpoint kinase ATR, we sought to further improve anti-tumor efficacy by combining PKMYT1 inhibition (RP-6306) with ATR inhibition (RP-3500)." (PMID 38410486, 2024). "We then co-stained for PKMYT1, TGF-α, SFRP1 and SFRP2 with the fibroblast markers: Collagen IVα1, PDGFR-α and α-SMA, which were respectively associated with ECM remodeling, immune modulation/M2 polarization and tumor proliferation/immune suppression." (PMID 37091166, 2023). "The results showed that PKMYT1 exerted a vital effect on tumor immunity and progression." (PMID 36803971, 2023). "In addition, PKMYT1 expression is related to the cell cycle and tumor microenvironment, suggesting that it can help guide the use of clinical antitumor drugs according to the database." (PMID 36793346, 2022). "We conclude that enhancing DNA replication stress in CCNE1-high tumours may be an effective approach to drive tumour regression in combination with PKMYT1 inhibition." (PMID 35444283, 2022). "The observation that replication stress can sensitize CCNE1-high tumour cells to PKMYT1 inhibition prompted us to test whether gemcitabine synergized with RP-6306 in vivo." (PMID 35444283, 2022). "Furthermore, we revealed that knockdown of PKMYT1AR or PKMYT1, but overexpression of miR-485-5p, inhibited the tumor sphere formation ability." (PMID 34856993, 2021). "We therefore conducted basic experiments to explore whether PKMYT1 can affect tumor radiosensitivity." (PMID 32411179, 2020). "Therefore, determining whether MMB–FOXM1-driven transcription can be targeted following the loss of CDK1 inhibitory phosphorylation may expand the range of tumours that could benefit from PKMYT1 inhibitors." (PMID 35444283, 2022). "Therefore, we hypothesized that PKMYT1 promotes tumor progression by regulating EMT, and cell cycle progression in ccRCC." (PMID 34959223, 2021). "RP‐6306 is a selective PKMYT1 inhibitor that suppresses the growth of CCNE1‐amplified cells and tumours." (PMID 41537447, 2026). "Here, the authors identify that CCNE1-amplified gynecological cancer is sensitive to combined PKMYT1 and ATR inhibition via CDK1 activation, resulting in premature mitosis, DNA damage, cell apoptosis and reduced tumour growth and metastasis." (PMID 40169546, 2025). "Collectively, these findings underscore the pathological significance of PKMYT1 in CML and its potential as a therapeutic target for inhibiting tumor cell proliferation and promoting mitochondrial dysfunction." (PMID 40279509, 2025). "RP-6306, a PKMYT1 inhibitor, effectively targets CCNE1-amplified tumor cells and shows enhanced efficacy when combined with agents like hydroxyurea or gemcitabine." (PMID 40664640, 2025). "Analysis on the expression of PKMYT1 and IGF2BP3 in the tumor distant metastasis group and lymph node metastasis group was performed using a tissue microarray and TCGA database, respectively." (PMID 35114989, 2022). "We also compared expression levels of paired normal and tumor samples in the TCGA dataset, and found down-regulated levels of WEE1 and WEE2 and up-regulated levels of PKMYT1 in tumors." (PMID 34959223, 2021).
tumor (continued). "To further shed light on the molecular mechanism how PKMYT1 affects the metastatic capability of ccRCC cells, we assessed the EMT phenotype, which plays crucial roles in tumor progression and is intently related to cell invasion and migration." (PMID 34959223, 2021). "To investigate how PKMYT1 and ATR inhibition are cooperating to activate CDK1, we measured levels of the CDK1 inhibitory phosphorylation at Thr14 (CDK1-pT14) in cell lines and tumor xenografts." (PMID 38410486, 2024). "Knockout of Pkmyt1 significantly reduced the tumor growth rate of the KPC but not KC xenografts in nude mice." (PMID 38570712, 2024). "Importantly, organoid cultures EOC989 and EOC884, which were derived from residual tumour cells from patients treated with chemotherapy (NACT), showed prominent synergistic response to the combined WEE1 and PKMYT1 inhibition." (PMID 37325550, 2023). "In addition, we further demonstrated overexpression of PKMYT1 in both RCC cell lines and tumor samples." (PMID 34959223, 2021). "According to the CPTAC data, the protein expression of PKMYT1, ETF1, ECT2, BUB1B, and RECQL4 in tumor tissues was significantly increased, while the expression of TFRC was significantly reduced, and the expression of COCH and TUBB2B did not change significantly (PITX1 and CDC6 were not included)." (PMID 33869220, 2021). "In the HPA data, compared with normal tissues, the expression of PKMYT1, ETF1, RECQL4, TUBB2B, and CDC6 in tumor tissues was remarkably upregulated, while the expression of TFRC and PITX1 was significantly downregulated (,ECT2, BUBB1B, and COCH were not included)." (PMID 33869220, 2021). "Also, despite the partially overlapping roles of WEE1 and PKMYT1, we did not observe that their expression would be upregulated in mutually exclusive fashion in tumours, supporting the rationale of combined targeting." (PMID 37325550, 2023). "However, there is no experimental evidence to prove the relationship between PKMYT1 and tumor radiosensitivity." (PMID 32411179, 2020). "WEE1 and PKMYT1 act as tumor suppressors in non-malignant eukaryotic somatic cells." (PMID 32958072, 2020). "Interestingly, while PKMYT1 depletion alone did not significantly impact long-term cell growth, its depletion markedly enhanced the effects of DNA damage, as evidenced by reduced cell growth in clonogenic survival assays and tumor xenograft models." (PMID 40702552, 2025). "However, the functional importance of PKMYT1 in tumor radiosensitivity has not yet been reported." (PMID 32411179, 2020). "Moreover, pharmacological inhibition of PKMYT1 shows efficacy in multiple PDAC cell models and effectively induces tumor regression without overt toxicity in PDAC cell line-derived xenograft and in more clinically relevant patient-derived xenograft models." (PMID 38570712, 2024). "As a direct downstream target of miR-485-5p, PKMYT1 was initially identified as a negative regulator of the normal cell cycle transition by inhibiting CDK1-cylin B complex via phosphorylating Tyr14/Tyr15, which is more critical for tumor cell proliferation." (PMID 34856993, 2021).
bacterial infection (1 paper, 2024). "Upregulation of GJB2, VNN1, DUSP4, SerpinB7, and IL10, and downregulation of PKMYT1, S100A4, GGTA1P, and SLC22A31 were most strongly associated with bacterial infection." (PMID 39395995, 2024).
PKMYT1 also shares sentences with these, for which no sentence is quoted: pancreatic ductal adenocarcinoma (3 papers); endometrial cancer (2); Chronic Lymphocytic Leukemia (1); Chronic Myeloid Leukemia (1); colon cancer (1); colorectal tumors (1); ductal breast carcinoma in situ (1); invasive breast carcinoma (1); invasive ductal breast carcinoma (1); invasive lobular breast carcinoma (1); male breast carcinoma (1); medullary breast carcinoma (1); prion disease (1); serous ovarian carcinoma (1); soft tissue sarcoma (1); squamous cell carcinoma of the cervix (1); tubular breast carcinoma (1).